THBS3 (thrombospondin 3)
Diseases named in the same sentence as THBS3 in open-access papers (continued):
Sharing a sentence is not in itself a finding about the gene and the disease.
tumor (14 papers, 2006 to 2025). "ITGA6 is a transmembrane protein involved in cell surface adhesion and signaling as well as in the regulation of proliferation, tumor invasion, and metastasis; similar to THBS3 and THBS4, ITGA6 is also expressed in the skin of sheep." (PMID 39913466, 2025). "As depicted in UMAP plots, THBS2, THBS4 and COMP were primarily expressed by fibroblasts, while THBS3 was predominantly expressed by tumor cells and fibroblasts, and THBS1 was predominantly expressed by fibroblasts, monocyte-macrophages and endothelial cells." (PMID 38827236, 2024). "Generally, THBS1 was primarily found in fibroblasts, endothelial cells, and mononuclear macrophage cells, THBS3 was mostly expressed in fibroblasts, tumor cells and T cells, whereas THBS2, THBS4 and COMP were mainly found in fibroblasts." (PMID 38827236, 2024). "The group with metastasis at diagnosis showed high levels of THBS3 expression in biopsy samples, demonstrating the importance of this gene in tumor growth and progression." (PMID 17022822, 2006). "A recurrent differential level of THBS3 expression was also observed when comparing biopsy and primary tumor resection samples from the same patients (n = 7) (p = 0.031)." (PMID 17022822, 2006). "There were also genes that are of insignificant expression in tumor cells that increase in expression in KO cells, e.g. THBS3, IL2RG, SPRR3, TGM2, HMOX1 and TMEM62 or are lower in expression in tumor cells and significantly decreased in KO cells such as MAN1A1, CES1, STCBP6, SIVA1 and TMEM40." (PMID 31797958, 2019). "This is the first report on the THBS3 gene working as a stimulator of tumor progression." (PMID 17022822, 2006). "THBS3 is also thought to be involved in immune processes such as antigen presentation and T cell differentiation, and may also play a role in tumor immunity." (PMID 36950136, 2023). "Combined with the immunohistochemical data from the database, we investigated the protein level changes of CAV2, FLT1, THBS3 and VAV3 in tumor samples and normal control samples." (PMID 36950136, 2023). "We found that CAV2 and VAV3 were significantly highly expressed in tumor samples, whereas the expression levels of THBS3 and FLT1 were not significantly altered in tumor samples." (PMID 36950136, 2023).
infection (5 papers, 2012 to 2024). The state of being infected such as from the introduction of a foreign agent such as serum, vaccine, antigenic substance or organism. "The results revealed that siRNA targeting THBS3 or THBS3 knockout effectively inhibited PRV-GFP (a recombinant PRV strain expressing GFP) infection in different cell lines." (PMID 38089700, 2023). "Moreover, both THBS3 antibody and soluble THBS3 protein treatment demonstrated similar antiviral activities against PRV-GFP infection, while THBS3 over-expression promoted PRV-GFP infection in PK15 cells." (PMID 38089700, 2023).
cardiac disease (2 papers, 2019). "Finally, the greater cardiac disease profile associated with Thbs3 overexpression was corrected by α7β1D heterodimer overexpression, directly demonstrating a causal relationship." (PMID 30622267, 2019). "However, Thbs3 is unique in that it functions opposite to Thbs1, Thbs2, and Thbs4, where it enhances cardiac pathology with disease stimulation, while mice deficient in Thbs3−/− were partially protected from cardiac disease." (PMID 30622267, 2019). "Consistent with the greater cardiac disease profile observed in Thbs3 DTG mice, we next examined Thbs3−/− mice and observed partial protection from cardiac disease-inducing stimuli." (PMID 30622267, 2019).
skeletal dysplasia (1 paper, 2015). Any Mendelian diseases that affects growth and development of the skeleton. "While mutations of Thbs5, better known as cartilage-oligomeric matrix protein (Comp), cause two different forms of skeletal dysplasia, the role of Thbs3 and Thbs4 in the skeleton are still poorly defined." (PMID 26629997, 2015).
THBS3 also shares sentences with these, for which no sentence is quoted: cyst (3 papers); bone tumor (1); brain disease (1); breast carcinoma (1); cholangiocarcinoma (1); dilated cardiomyopathy (1); glioblastoma (1); heart failure (1); hemangiosarcoma (1); hyperuricemia (1); leukemia (1); liver cyst (1); lung carcinoma (1); lymphoma (1); testicular germ cell tumor (1); thrombosis (1); worm infections (1).